GNAQ (G protein subunit alpha q)
Diseases named in the same sentence as GNAQ in open-access papers (continued):
Sharing a sentence is not in itself a finding about the gene and the disease.
uveal melanoma (continued). "The frequencies of GNAQ and GNA11 somatic mutations in uveal melanoma were 18% (9/50) and 20% (10/50), respectively." (PMID 25280020, 2014). "These G-alpha protein mutations occur in the genes GNAQ and GNA11 and are seen at a high frequency in uveal melanomas, those melanomas that begin in the eye." (PMID 25030020, 2014). "Based on these data, we propose a model in which GNAQ/GNA11 mutations, detected in the Gα subunit of heterotrimeric G proteins in the majority of primary uveal melanomas, are responsible for the activation of MAPK pathway under normoxic conditions." (PMID 25166211, 2014). "Somatic mutations in BRAF gene have been described as key genetic alterations in skin melanoma development, whereas GNAQ gene was described as an oncogene in uveal melanomas." (PMID 23904987, 2013). "Activating mutations in exon 4 (R183) and exon 5 (Q209) of GNAQ and GNA11 are almost exclusively found in uveal melanoma, thus providing a highly specific marker for the presence of circulating tumor DNA (ctDNA)." (PMID 23634288, 2013). "BRAF and NRAS mutations are absent in melanomas arising in the uveal layer of the eye, but mutually exclusive somatic mutations in the heterotrimeric G protein alpha-subunit, GNAQ, or in GNA11, are present in the great majority of uveal melanomas." (PMID 22515704, 2012). "Prompted by similar phenotypes in mice harboring germline mutations in GNAQ and GNA11, GNA11 was also evaluated in a series of uveal melanomas, blue nevi and other nevi." (PMID 25562798, 2012). "For over 40% of uveal melanomas, MAPK activation is driven by mutation of GNAQ, a gene that encodes for the alpha subunit of a heterotrimeric G protein complex (αβγ) that mediates signaling between G-protein–coupled receptors (GPCRs) and downstream effectors." (PMID 22808163, 2012). "Most harbor GNAQ or GNA11 mutations, linking them genetically to uveal melanoma." (PMID 41183565, 2026). "The whole-genome CRISPR screening in Guanine nucleotide-binding protein G(q) subunit alpha (GNAQ) mutant uveal melanoma (UM) cells showed that a member of Gα protein family Gαq promoted PI3K/AKT signaling pathway through focal adhesion kinase (FAK) for cell growth and survival." (PMID 38816739, 2024). "In addition, mutations in GNAQ and GNA11 occurred in the majority of uveal melanomas found in this study, which is consistent with the findings of previous research." (PMID 37649078, 2023). "Indeed, hot spot–activating mutations in GNAQ/GNA11, encoding Gαq proteins, are known to be driver oncogenes in uveal melanoma (UM), for which there are limited effective therapies currently available." (PMID 36596361, 2022). "Mutations in the GNAQ and GNA11 genes, which encode guanine nucleotide-binding protein G(q) subunit alpha and guanine nucleotide-binding protein subunit alpha-11, are detected in more than 80% of primary uveal melanomas." (PMID 35804893, 2022). "However, the effect of GNAQ p.Arg183Gln in MAPK signal transduction appears to be weaker in terms of activation of downstream effectors than the effect of the more frequently detected GNAQ p.Gln209Leu substitution in uveal melanoma tissue." (PMID 36293054, 2022). "We initially examined TNFα signaling in response to exogenous TNFα in 40 melanoma cell lines, including 31 cutaneous (11 BRAF-mutant, 10 NRAS-mutant, 10 BRAF/RAS WT) and nine uveal melanoma cell lines (five GNAQ-mutant, three GNA11-mutant and one GNAQ/GNA11 WT)." (PMID 34073253, 2021). "Some cases presented with mutations usually linked to uveal melanomas (GNAQ, GNA11, SF3B1, BAP1), but these mutations did not co-occur, suggesting a different tumorigenesis process than in UM." (PMID 34359736, 2021). "Uveal melanoma is frequently associated with mutations in the CYSLTR2, PLCB4 and GNAQ/GNA11 genes." (PMID 34359771, 2021). "Among these genes, GNAQ was reported to be related to uveal melanoma progression." (PMID 34124063, 2021).
uveal melanoma (continued). "Recent studies have shown that GNAQ mutations appear repeatedly in certain types of non-Hodgkin lymphoma, and other studies have suggested that MYC alterations are associated with aggressive non-Hodgkin lymphoma or a poor prognosis of uveal melanoma." (PMID 34682867, 2021). "Nevertheless, these data do not explain the GNAQ/GNA11 selective mutational pressure observed in uveal melanoma compared to cutaneous melanoma or why they are considered to be oncogenic." (PMID 32532044, 2020). "Mutation of GNAQ is strongly associated with the non-T cell-inflamed phenotype across tumors and predominately in uveal melanoma, a subset of melanoma known to be resistant to immune-checkpoint blockade (FDR-adjusted P = 0.050)." (PMID 33106165, 2020). "Furthermore, molecular alterations have also been identified in other genes, such as c-KIT and GNαQ (Guanine Nucleotide-binding protein G(q) subunit alpha (Gαq)), which have been described in mucosal and uveal melanoma subtypes, respectively." (PMID 32013263, 2020). "Furthermore, as a consequence of GNAQ/GNA11 mutation, an upregulation of MET has been implicated in uveal melanoma." (PMID 31109147, 2019). "Third, the majority of uveal melanoma is driven by mutations in GNAQ and GNA11, as opposed to Braf and Nras mutations in cutaneous melanoma." (PMID 31320995, 2019). "In this study, we examined interferon-γ (IFNγ) responses in a large panel of immune checkpoint inhibitor-naïve melanoma cells with defined genetic drivers; BRAF-mutant (n = 11), NRAS-mutant (n = 10), BRAF/NRAS wild type (n = 10), and GNAQ/GNA11-mutant uveal melanomas (UVMs) (n = 8)." (PMID 29977240, 2018). "Mutations in GNAQ and GNA11 account for up to 83% of all uveal melanoma, which suggests that inhibition of YAP/TAZ activity, either directly or by blocking pathways downstream of GPCRs, may be an effective treatment for this cancer." (PMID 29642615, 2018). "While a few GNAQ and GNA11 mutations were identified, they presumably represent functionally non-relevant bystander mutations, as none of the identified mutations were the activating R183 or Q209 mutations known to occur in uveal melanomas." (PMID 29559732, 2018). "Another recent study reported the recurrent mutation in PLCB4, occurring in about 4% of uveal melanomas; importantly, PLCB4D630Y mutations are mutually exclusive with mutations in GNA11 and GNAQ, in line with the observation that PLCB4 is a canonical downstream target of GNA genes." (PMID 29156643, 2017). "Mutations in the G-α-proteins GNAQ and GNA11 that occur in 91% of uveal melanoma also activate MAPK and PI3K/AKT pathways, which implies that the combination of MEK and AKT inhibitors may also be profitable for this patient group." (PMID 28938534, 2017). "Furthermore, GNAQ and GNA11 mutations blocking GTP hydrolysis were identified in melanocytic neoplasms such as uveal melanoma and blue nevi." (PMID 27034005, 2016). "Thus, GNAQ mutant uveal melanoma cell lines appear more sensitive to the combination of MEK and MET." (PMID 24551032, 2014). "Considering the genetic variations and their role in tumor genesis in different ethnic groups, we investigated the status of GNAQ and GNA11 mutations in uveal melanoma of Chinese patients to decrypt potential oncogenic differences between Caucasian and Chinese populations." (PMID 25280020, 2014). "Koopmans and his colleagues reported that patient survival in uveal melanoma was not correlated with oncogenic mutations in GNAQ and GNA11." (PMID 25280020, 2014). "Activation of MAPK and AKT/mTOR pathways was found in a series of uveal melanomas, but in those cancers this activation did not relate with the presence of GNAQ mutation." (PMID 23904987, 2013). "In addition, constitutively active, oncogenic mutations in either GNAQ or GNA11 are found in ∼75% of common nevi of the dermis and in ∼83% of uveal melanomas." (PMID 23555837, 2013).
uveal melanoma (continued). "Considering that about 80% of primary tumors or uveal melanoma metastases show mutant GNA11 or GNAQ genes 18, it is plausible that only a few of the remaining 13 patients had tumors without one of these mutations, and therefore, were uninformative for our study." (PMID 23634288, 2013). "This is supported by the finding of a constitutively active GNAQ mutation in an NF1+/− uveal melanoma, which otherwise might be redundant, if EDNRB/GNAQ signaling completely overlapped with NF1." (PMID 23555837, 2013). "Although the MAP-kinase cascade is a mutational target in several tumor entities, activation of this pathway by mutations in either GNAQ or GNA11 is specific for uveal melanomas and other nonepidermic melanocytic lesions like blue nevi 19,20,21." (PMID 23634288, 2013). "Also like GNAQ, although GNA11 is primarily viewed as relevant to uveal melanoma, anecdotal reports have found mutations in this gene in non-uveal melanoma patients." (PMID 21479172, 2011). "Therefore, we set forth to investigate whether GNAQ/GNA11-driven uveal melanoma cells also exhibit heightened sensitivity to PAK inhibition." (PMID 41154654, 2025). "Mutually exclusive mutations in G Protein Subunit Alpha Q (GNAQ) and G Protein Subunit Alpha 11 (GNA11), members of the Gαq family of proteins, frequently initiate neoplastic proliferation of uveal melanocytes, serving as a primary driver in uveal melanoma pathogenesis." (PMID 41160198, 2025). "Thus, GNAQ and GNA11 are essential biomarkers for uveal melanoma in diagnostic panels." (PMID 37576814, 2023). "Expansion into publicly available bulk and single cell uveal melanoma sequencing data allowed to evaluate our findings in independent cohorts of primary and metastatic tumours and to study the role of wild-type CYSLTR2 in melanomas with a mutation in GNAQ, GNA11 or PLCB4." (PMID 33588787, 2021). "Unlike skin melanomas, BRAF mutations are extremely rare in uveal melanomas, where the vast majority show mutations in the genes GNAQ and GNA11 that activate the mitogen-activated protein kinase (MAPK) pathway and, consequently, result in increased cell proliferation." (PMID 32911759, 2020). "Thus, GNAQ, GNA11, PLCB4, and CYSLTR2 form four modules of independent mutated uveal melanomas." (PMID 29156643, 2017). "A recent study reported recurrent mutations of G-protein-coupled receptor CYSLTR2 (cysteinyl leokotriene receptor 2) exclusively occurring in uveal melanoma patients not displaying GNAQ, GNA11, and phospholipase C, beta 4 (PLCB4) mutations (in about 40% of these patients)." (PMID 29156643, 2017). "Oncogenic mutations in GNAQ and GNA11 result in constitutive activation of these proteins and downstream signalling of pathways such as the YAP pathway, the phosphoinositide-3 kinase/AKT and the Ras/Raf/MEK/ERK pathway, thus playing a key role in the development and progression of uveal melanomas." (PMID 26059332, 2015). "Constitutive MAPK activation seems to be a common event in both skin and uveal melanomas, although it occurs through different mechanisms: in skin melanoma, through BRAF and NRAS activating mutations, and in uveal melanoma MAPK activation can occur through GNAQ activating mutations." (PMID 23904987, 2013). "Responses were seen in tumours harbouring BRAF fusions, GNA11, GNAQ, KRAS, NF1, and NRAS alterations, most frequently in low-grade serous ovarian cancer, central nervous system tumours, and uveal melanoma." (PMID 41664938, 2026). "Guanine nucleotide‐binding protein, Q polypeptide (GNAQ) activates YAP via FAK, driving uveal melanoma progression." (PMID 40066231, 2025). "Rare mutations in CYSLTR2 and PLCB4, which function upstream and downstream of GNAQ/GNA11, respectively, have also been identified, demonstrating the importance of this pathway in uveal melanoma oncogenesis." (PMID 37966164, 2023).
uveal melanoma (continued). "In uveal melanoma cells, the TRIO-RHO/RAC signaling axis lies downstream of oncogenic GNAQ/11 and stimulates YAP, a critical component of the Hippo signaling pathway, which in turn controls cell proliferation 50,69." (PMID 35673577, 2022). "The structurally similar FR900359 and YM-254890 inhibit oncogenic GNAQ/GNA11 and promote potent cell cycle arrest and apoptosis in uveal melanoma." (PMID 35352024, 2022). "This review aims to provide a current comprehensive view of what we know about GNAQ and GNA11 genes on oncogenesis, prognosis and therapeutic opportunities in uveal melanoma." (PMID 35804836, 2022). "The potential role of wild-type CYSLTR2 in GNAQ, GNA11 or PLCB4 mutant uveal melanomas was studied in publicly available bulk and single cell sequencing data." (PMID 33588787, 2021). "It has been reported that GNAQ and ARF6 control the subcellular localization and transactivation of β-catenin in uveal melanoma cells." (PMID 31320995, 2019). "Recently ARF6 has been found to be a major signaling node in GNAQ mutant melanoma, and blockade of ARF6 has been shown to inhibit multiple pathways activated in uveal melanoma." (PMID 31320995, 2019). "Initiating mutations in either Guanosine Nucleotide-binding Protein Q gene (GNAQ) or its paralogue, Guanosine Nucleotide-binding Protein Alpha-11 Gene (GNA11), act as a paramount driver in the oncogenic process and are present in 80–90% of uveal melanomas." (PMID 38732371, 2024). "Uveal melanoma (UM) cells are characterized by the presence/absence of BAP1 protein and mutation in the GNAQ/GNA11 genes." (PMID 39195238, 2024). "Expressions of GNAQ, ARHGEF11, RHOJ and the fourteen selected signaling partners, analyzed in TCGA uveal melanoma patients and uveal melanoma cell line datasets, revealed parallelism, with GNAQ, ARHGEF11, and RHOJ being among the highest expressed transcripts in both groups." (PMID 37958718, 2023). "ctDNA in non-cutaneous melanoma—In uveal melanoma (UM), recurrent mutations affecting GNA11, GNAQ, PLCβ4 or CYSLTR2 are found in the majority of patients and, even if they are not determinants of prognosis, they can represent targetable mutations in the blood." (PMID 38201222, 2023). "Their effect has not been precisely studied, but their exclusivity with the GNAQ, GNA11, and CYSLTR2 mutations and PLCβ4 being downstream of these proteins suggest that PLCβ4 mutations have a similar effect on the oncogenicity of uveal melanomas." (PMID 35158973, 2022). "Mechanistically, oncogenic GNAQ/11 promotes ARF6 activation, which orchestrates the activation of a broad range of events, including the activation of the PKC/ERK and HIPPO/YAP signaling pathways to control the proliferation of uveal melanoma cells." (PMID 35673577, 2022). "For example, GTF2I is specific to thymomas, whereas GNAQ and GNA11 are specific to uveal melanomas." (PMID 35975235, 2022). "Uveal melanomas driven by mutant GNAQ/GNA11 (Gαq proteins) activate FAK through TRIO-RHOA non-canonical Gαq; FAK, in turn, activates YAP, which promotes aberrant uveal melanoma growth." (PMID 35159327, 2022). "No somatic mutations in R183 in exons 4 of GNAQ and GNA11 were found in 63 Chinese uveal melanoma samples." (PMID 35693877, 2019). "Although uveal melanoma does not express direct changes in the BRAF gene (rendering its indication of vemurafenib and dabrafenib unfeasible), it has mutations in the GNAQ or GNA11 (G protein subunit encoding) genes within 80% of cases." (PMID 28573105, 2017). "The landmark studies on the association of uveal melanoma with GNAQ and GNA11 mutations were conducted in Caucasian populations while the status of GNAQ and GNA11 mutations in uveal melanomas of Chinese has not been investigated yet." (PMID 25280020, 2014). "In summary, we report the absence of germ-line mutations in exon 5 of GNAQ and GNA11 in familial melanoma pedigrees with an increased incidence of uveal melanoma and/or blue nevi." (PMID 23825798, 2013).
uveal melanoma (continued). "Furthermore, only one subclonal variant of unknown significance in GNAQ and no GNA11 mutations, usually present in uveal melanoma, were found." (PMID 31500314, 2019). "The lack of GNAQ and GNA11 germ-line mutations in familial melanoma pedigrees with an increased incidence of uveal melanoma and blue nevi further is supportive of the importance of sporadic mutations in these genes in blue nevi and uveal melanoma as previously published." (PMID 23825798, 2013).
melanoma (100 papers, 2011 to 2025). A malignant, usually aggressive tumor composed of atypical, neoplastic melanocytes. "For example, nearly one-half of melanomas arising in the epidermis harbor oncogenic mutations in the BRAF gene, while almost half of the melanomas arising in the uvea harbor oncogenic mutations in the GNAQ/GNA11 genes." (PMID 38360887, 2024). "Subungal melanoma had a frequently mutated gene, named G protein subunit alpha Q. Patients with subungual melanoma show better survival than patients with acral melanoma." (PMID 37686691, 2023). "GNAQ, a member of the alpha subunit of the G protein, is mutated in approximately 80% of melanoma patients." (PMID 35601407, 2022). "Histological and molecular genetic analyses revealed an epithelioid-cell-type melanoma with complete circumferential involvement of the ciliary body and, so far, unreported GNAQ and SF3B1 mutations in ring melanoma." (PMID 35692773, 2022). "GNAQ encodes the alpha subunit of a heterotrimeric G-protein and mutations are associated with certain melanoma cancers." (PMID 34944895, 2021). "It is thought that mutations in SF3B1 arise as a second genetic change in UM and blue nevus-like melanoma, after initial mutation in GNAQ or GNA11; however, SF3B1 changes can be driver mutations in MDS." (PMID 30558566, 2018). "In this report choroidal, ciliochoroidal and iridociliary melanomas were analyzed for GNAQ and GNA11 mutations which were subsequently correlated to the location of tumor origin." (PMID 26368812, 2015). "This study investigated whether NF1 loss can collaborate with oncogenic GNAQ to promote melanoma in the dermis or eyes, in which the Gαq pathway is almost always activated." (PMID 39804140, 2025). "GNAQ is implicated in canine melanomas and T cell lymphomas by different researchers." (PMID 30517191, 2018). "Furthermore, PI3KCA activating mutations common in many cancers have been detected in ≤3% of melanomas, while recently GNAQ/GNA11 mutations have been detected in uveal melanomas in up to 34–48% compared to <1% of cutaneous melanomas." (PMID 25695059, 2015). "Furthermore, other mutations, namely, N-RAS, KIT, and GNAQ, should be sequenced according to distinct melanoma specific subtypes and clinical aspects." (PMID 24591764, 2014). "Summary of BRAF, NRAS, and GNAQ mutational status in melanoma cell lines." (PMID 23904987, 2013). "Moreover, as aberrations in G-protein activating subunits have been shown to act as driver mutations implicated in multiple cancers, the use of siRNA to target and downregulate mutated GNAQ (degree = 8) in several cancers, in particular melanoma, has been also explored." (PMID 35913978, 2022). "Transcriptional programs enriched in BRAF- versus GNAQ-driven melanoma overlap with specific melanocyte progenitor populations." (PMID 40950146, 2025). "Our results highlight that mitfa expression does not directly reflect Mitfa activity, as mitfa-target genes are more highly expressed in BRAF-positive melanoma despite lower mitfa expression compared to GNAQ-positive melanoma." (PMID 40950146, 2025). "Acral melanomas harbor KIT, NRAS, and BRAF mutations, mucosal melanomas KIT and NRAS mutations, and uveal and melanomas arising in blue nevi uniquely have GNA11 and GNAQ mutations." (PMID 37841001, 2023). "In this study, as an extension to our previous work on head and neck mucosal melanomas, we aimed to investigate the BRAF, NRAS, KIT, TERT and GNAQ/GNA11 mutation status of 15 AMs, as well as their clinicopathologic features." (PMID 35642348, 2023).